IFNG (interferon gamma)
Diseases named in the same sentence as IFNG in open-access papers (continued):
Sharing a sentence is not in itself a finding about the gene and the disease.
tumor (continued). "Consequently, anti-tumor effector molecules, such as IL2, IFNγ, TNFα, and granzyme B (GZMB), is dramatically downregulated in the CTLs and NK cells, and immune exhaustion and dysfunction are provoked locally and systemically in the host." (PMID 36211375, 2022). "To determine whether IFNγ plays a role in the CD4 T cell–mediated antitumor effect, we treated tumor-bearing mice with Marilyn CD4 T cells in the presence of either αIFNγ or control IgG1 antibodies." (PMID 35903540, 2022). "After binding to 4-1BB on tumor cells, NK cells had an increased CD73 surface expression, which triggered STAT3 activation and TGF-β/IL-10 secretion correlating with reduced CD4+ T cells proliferation and IFNγ production." (PMID 35769460, 2022). "We observed varying levels of IFNγ release by the CAR h3 T cells in response to each of the tumor-types, but none by the UTD T cells." (PMID 35990626, 2022). "It was found that the combination therapy or monoclonal antibody alone can slow down tumor growth, the combination therapy did not significantly improve the efficacy, and the tumor grafts increased IFNγ-secreting human T cells and decreased human Treg cells." (PMID 36012461, 2022). "The secretion of IFN-γ was higher in RA+ CAR-T cells than in RA− CAR-T cells, although transcriptome profiling showed that IFNG expression has been already downregulated in RA+ CAR-T cells on day 3 of co-culture with tumor cells." (PMID 35154098, 2022). "HLA Class II alleles are highly associated with the CD4+ T cells; CD4+ T cells primarily mediate anti-tumor immunity by providing help for CD8+ CTL and antibody responses, as well as via secretion of effector cytokines such as interferon-γ (IFNγ) and tumor necrosis factor-α (TNFα)." (PMID 35967400, 2022). "Assessment of the tumor immune infiltrate showed that subcutaneous tumors of mice with liver metastases had reduced CD8+ T cell expression of activation markers including ICOS, PD-1 and CTLA-4, as well as expression of intracellular IFNγ." (PMID 36466910, 2022). "Interestingly, significantly fewer MDSCs, while abundant IFNγ+CD8+ T cells, were found in the tumor tissues from KO→WT BM chimeric mice than WT→WT BM chimeric mice." (PMID 34976216, 2022). "In addition, nociceptor-ablated mice showed an increase in the total number and relative frequency of cytotoxic (IFNγ+, TNF+or IL-2+) tumour-infiltrating CD8+ T cells, but a reduced proportion of PD-1+LAG3+TIM3+ CD8+ T cells." (PMID 36323780, 2022). "In addition, TGF-β reduces the cytotoxicity of CD8+ T cells by impairing their secretion of perforin, granzyme, and IFNγ, which are imperative for CTL-mediated tumor killing." (PMID 35720407, 2022). "The overexpression of CCL3 in murine colon cancer cells or the subcutaneous injection of CCL3 near the established tumor does not modify the proportion of CD8 T cells but favors their capacity to produce IFNγ." (PMID 36429101, 2022). "Here we analyzed a phenomenon whereby tumor-specific T cells induce PD-L1 upregulation in autologous MDS cells in short-term culture, through a mechanism that is cell-contact-independent and partially IFNγ-dependent." (PMID 35992887, 2022). "Thus, MB49 TAMs can present tumor antigens in situ to effector CD4 TILs, triggering mainly an IFNγ response." (PMID 35903540, 2022). "Furthermore, TIGIT was validated to be expressed on MCL tumor cells after BA relapse and TIGIT expression on tumor cells suppressed IFNγ production by T cells." (PMID 36163179, 2022). "Inhibition of STAT3 and EGR1, but not MAPK3 and EGR2, significantly abrogated the capacity of tumor cells to form cell-in-cell structures upon incubation with IFNγ-stimulated T cells and with T cell secreted granules." (PMID 36124553, 2022). "The main producers of IFNγ are antigen-specific CD8+ T-cells; therefore, the results suggest that the TIL populations are composed of functional effector T-cells that have the machinery to perform anti-tumour roles within the TME." (PMID 35158816, 2022).
tumor (continued). "The absence of CXCR3 seems not to interfere with the ex vivo-specific lysis against tumor cells (OT-I CD8 T cells/OVA-expressing tumor cells) nor with the IFNγ, TNFα or Granzyme B expression." (PMID 36429101, 2022). "Of note, the increased IFNγ in TILs could also promote PD-L1 expression and the apoptosis of LEC, which might affect Treg or Teff tumor egress." (PMID 35449134, 2022). "Regarding the establishment of tumor-promoting inflammation, KRAS was shown to be capable of inducing cytokine secretion such as IL-6 and reduced secretion of IFNγ, TNF, and IL-2 by different stromal cell types, e.g., fibroblasts, myoblasts and epithelial cells." (PMID 35965494, 2022). "Evidence has demonstrated that lentinan decreased tumor vascular function in a non-T-cell dependent manner by increasing IFNγ production, and showed anti-tumor effect in LAP0297 lung tumor model." (PMID 36159787, 2022). "For IFNγ, a dose sufficient to up-regulate HLA-A/PD-L1 and sensitize the tumor to paclitaxel rather than inducing a strong anti-tumor response was utilized." (PMID 35459800, 2022). "Upon initial contact with tumor antigen, activated CD8+ cytotoxic T cells express a plethora of cytokines based on their subtypes and exposure to polarizing cytokines including interferon gamma (IFNγ), Granzyme B, and Perforin." (PMID 35372046, 2022). "Surprisingly, other immune cell populations and effector cell functions that are typically altered through tumor PDL1 depletion (e.g., IFNγ+ CD8+ T cells, Granzyme expression) were unaffected by cefepime treatment, which suggests differential immune consequences of PDDs." (PMID 35563520, 2022). "Additionally, NK cell activation leads to the release of large amounts of IFNγ, TNF, and chemokines that exert strong anti-tumor functions and recruit immune cells into the tumor." (PMID 36372017, 2022). "We detected increased levels of cytokines such as IFNγ and TNFα, which could favor the increase in infiltrating CD8+ T cells observed in the tumor regions." (PMID 35326737, 2022). "In addition, interferon gamma released by CD8+ T cells downregulates the expression of SLC3A2 and SLC7A11, impairing the uptake of cystine by tumor cells and thus promoting lipid peroxidation and iron weakness in tumor cells." (PMID 36012134, 2022). "Tumour infiltration of CD8+ T cells was also enhanced by napabucasin treatment, and exhibited lower levels of LAG‐3, PD‐1 and high levels of Granzyme B, Perforin, IFNγ in the napabucasin‐treated mice than in the control group." (PMID 35665592, 2022). "IFNγ from CD8+ T cells and arachidonic acid (AA) from the tumor microenvironment mediate tumorigenic ferroptosis through acyl-CoA synthetase long-chain family member 4 (ACSL4) while targeting tumor ACSL4 reportedly improved immune checkpoint blockade treatment sensitivity." (PMID 36158661, 2022). "We detected upregulated levels of cytokines such as IFNγ (unpaired t-test, p < 0.0001) and TNFα (unpaired t-test, p = 0.0003), which could favor the increase in infiltrating CD8+ T cells observed in the tumor regions of Sftpc-KO mice." (PMID 35326737, 2022). "Of note, the main CD4+ and CD4− iNKT cell subsets were not equally effective in tumor control: in fact, liver-derived CD4− iNKT cells were found to be the main mediators of tumor immune surveillance in vivo, by sustaining a TH1-type CD8+ T and NK cell-mediated immune response via IFNγ production." (PMID 35615083, 2022). "Regardless of tumor type, patients with values of sTIM3, IFNα, IFNγ, IL1β, IL1α, IL12p70, MIP1β, IL13, sCD28, sGITR, sPDL1, IL10 and TNFα below the median had longer overall survival (p<0.05)." (PMID 36405727, 2022). "Moreover, IFNγ-induced PD-L1 lowers the required level of EMT-inducing signal, leading to an overall larger probability of EMT in tumours with a high IFNγ expression compared with tumours with a low expression." (PMID 36397970, 2022).
tumor (continued). "Since the increased IFNγ production during incomplete C11BM inhibition provokes PD-L1 expression in the melanoma cells, the combination of MALT1 inhibitors and anti-PD1 immune checkpoint therapy exhibits synergistic effects in the inhibition of tumor growth." (PMID 35203553, 2022). "An antiangiogenic effect has been observed to occur through the release of IFNγ by CD4+ Th1 cells, but the exact mechanism of action may be distinct when comparing different tumor models." (PMID 36159781, 2022). "The negative effect of tumor hypoxia on radiotherapy efficacy is partially due to hypoxic inhibition of IFNγ production and the impairment of hypoxic cells to response to IFNγ." (PMID 35251003, 2022). "Overall, these data show that IFNγ and TNFα secreted from T cells during TDCC can induce TYMP gene transcription followed by TP protein synthesis in MKN45, which efficiently converts capecitabine to 5′-FU at the tumour site." (PMID 36071036, 2022). "The tumor type and amount of IFNγ produced seem to determine the extent of antiangiogenic effect, with large amounts of IFNγ leading to vascular regression and hypoxia rather than normalization and normoxia." (PMID 35712656, 2022). "Restimulation of expanded TILs with autologous tumor cells revealed that GEN1046-expanded CD8+ TILs contained greater proportions of cells that upregulated 4-1BB and IFNγ/CD107a upon restimulation compared with atezolizumab and IL2 alone, which was dependent on MHC I." (PMID 35176764, 2022). "Cells without STAT1 gene cannot be induced to produce SOCS1 due to IFNγ signalling pathway obstruction, which may induce malignant cell proliferation, thus SOCS1 is also regarded as a tumor inhibitor." (PMID 36185620, 2022). "Similarly, B1a Bregs (CD19+CD5+CD43+) have been described to use IL-10 to inhibit IFNγ and TNFα production by CD8+T cells thus negatively regulating tumour immunity against melanoma cells." (PMID 35350071, 2022). "The exhausted tumour-specific T-cells do not express characteristic pro-inflammatory cytokines such as IL-2, TNFα, and IFNγ, but instead produce the inhibitory receptors such as programmed death 1 (PD-1) and cytotoxic T-lymphocyte associated protein 4 (CTLA4)." (PMID 36140243, 2022). "The tetanus toxoid induced attraction of CD4 T cells, with increased production of IFNγ, perforin, and granzyme B in the TME, while gemcitabine was used to reduce immune suppression in the TME, which resulted in reduced tumor burden by 80% compared to untreated mice." (PMID 35757741, 2022). "Radiotherapy-activated ATM and IFNγ from immunotherapy-activated CD8+ T cells would synergistically enhance ferroptosis and tumor lipid oxidation, indicating the correlation between ferroptosis agonists and chemoradiotherapy via immunotherapy for the first time." (PMID 36439512, 2022). "These immune escape mechanisms are related to the lack of neoantigens, impaired intra-tumor immune infiltration, impaired IFNγ signaling, and severe T-cell exhaustion, which exhibit a “cold” TIME." (PMID 35328658, 2022). "WAP can enhance phagocytosis by macrophages, while ALP enhances the activation of lymphocytes to increase the release of cytokines such as interleukin -2 (IL-2), interleukin -12 (IL-12), interferon-gamma (IFN-γ) and TNF-α, which together induce the necrosis and apoptosis of tumor cells." (PMID 36278230, 2022). "This study also showed that in contrast to IFNγ, type I IFNs do not require tumor cell responsiveness to exert the antitumor immune response." (PMID 35251003, 2022).
tumor (continued). "Specifically, interferon gamma released from CD8+ T cells restrain the synthesis of GSH through downregulating SLC3A2 and SLC7A11, therefore leading to the accumulation of peroxidated phospholipid and ferroptosis in tumor cells." (PMID 35874826, 2022). "Furthermore, IFNγ downregulates the expression of SLC3A2 and SLC7A11, two subunits of the glutamate–cystine antiporter system xc−, impairs the uptake of cystine by tumor cells, and subsequently promotes tumor cell lipid peroxidation and ferroptosis." (PMID 34385592, 2022). "pIκB, IκB, pIκB/IκB ratio, COX2, PPARγ, IL-4R and IFNγ protein levels were studied in both tumor and non-tumor adjacent tissues in all stages from CRC patients." (PMID 36139645, 2022). "Programmed death-ligand 1 (PD-L1) expression (Tumor Area Positivity [TAP] ≥ 5%), interferon gamma (IFNγ)-related gene signature, gene expression profile, tumor mutational burden (TMB), and gene hyperamplification (HA) were analyzed for correlation with tislelizumab." (PMID 35778636, 2022). "The IFNγ secreted by CD8+ T cells downregulates the expression of SLC7A11 and SLC3A2, and therefore attenuates the uptake of cystine by tumor cells, consequently enhancing lipid peroxidation in tumor cells, ultimately increasing ferroptosis." (PMID 35531466, 2022). "Further, when activated CD4+ and CD8+ T cells were detected by co-staining with IFNγ, the distribution tendency was similar to that of total CD4+ and CD8+ T cells in the tumors, indicating that the TILs are activated to kill tumor cells in the TME." (PMID 36405748, 2022). "Besides, the functional CD8+ T cells, which produce various cytokines (TNFα, IFNγ, GZMB, and IL2), were increased in the tumor from VEGF-C mRNA group." (PMID 35301438, 2022). "Additionally, interferon-gamma, a cytokine involved in immune challenge, increased secretion of ADMA in tumor cells, a process attenuated by an autophagy inhibitor." (PMID 36376929, 2022). "IFNγ levels presented a tissue effect, being tumor tissue IFNγ levels higher than non-tumor adjacent tissue." (PMID 36139645, 2022). "There was no significant increase in total CD8+ T cells or IFNγ+ CD8+ T cells per g of tumor as a consequence of anti-PD-1 treatment in mice containing or lacking NK cells." (PMID 36531040, 2022). "Moreover, we demonstrated that ERY974-induced cytokines, such as IFNγ and TNFα secreted from T cells activated by ERY974 induced TP expression in tumours." (PMID 36071036, 2022). "For instance, IFNγ release during CAR T cell activation and killing of tumor cells induces upregulation of immune checkpoint proteins (e.g., PD-L1) which attenuate the anti-tumor function of cytotoxic T cells." (PMID 35741103, 2022). "The results were highly consistent with the qPCR assay, showing that the percentages of IFNγ-eYFP+ T cells did not undergo changes with 4T1 tumor growth in either spleen or lungs." (PMID 35126389, 2022). "Tumor-expressed PD-L1 is regulated by multiple mechanisms, including activation of the phosphatidylinositol 3-kinase (PI3K) signaling pathway and TIL-secreted interferon gamma (IFN-γ)." (PMID 35968275, 2022). "Flow cytometry analysis of resected 4T1 tumors collected from a separate experiment showed that the combination treatment resulted in increased expression of IFNγ, TNFα, and granzyme B in intratumoral CD8+ T and NK cells, as well as an overall increase in tumor-infiltrating CD8+ T cells." (PMID 35840558, 2022). "This formation is mediated predominantly by IFNγ-activated T cells, which subsequently induce phosphorylation of the transcription factors signal transducer and activator of transcription 3 (STAT3) and early growth response-1 (EGR-1) in tumor cells." (PMID 36124553, 2022). "While, IFNγ can impair the elimination of lipid peroxides (LPO) via downregulating the expression of SLC7A11 and SLC3A2, leading to a massive accumulation of LPO in tumor cells resulting in ferroptosis." (PMID 36349201, 2022).
tumor (continued). "In tumour-bearing mice, MDSCs induce the emergence of a population of splenic PD1-PD-L1+CD19+IL-10-secreting B cells that inhibit effector T cell proliferation and IFNγ expression." (PMID 35350071, 2022). "One striking difference was the increase in IFNγ + and granzyme B (GZMB) expressing cytotoxic CD8s after vaccination, which could have potential anti-tumour activity." (PMID 36307410, 2022). "The previous reports demonstrated that PD-L1 protects LN LECs and tumor cells from apoptosis, while we observed that loss of PD-L1 in dermal LEC increased cell viability and prevented apoptosis induced by IFNγ but not TNFα." (PMID 35449134, 2022). "Strikingly, compared to parental and control cells, tumour cells lacking Stub1 displayed significantly higher, IFNγ-dependent, MHC-I on cell surface." (PMID 35982220, 2022). "Elicitation of PCa-TDSFs by inflammatory factors like interferon gamma (IFN-γ) and TNF-α might be responsible for rendering a tumor untreatable." (PMID 36059977, 2022). "We found that the MC2 subtype with the best prognosis has higher T cell lytic activity and lower angiogenesis, IFNγ, and TIDE scores, indicating that this subtype has stronger immunogenicity and a good tumor microenvironment and is more likely to benefit from immunotherapy." (PMID 35800989, 2022). "Conversely, ligand IFNG and its related pro­inflammatory cytokine TNF, and ligands related to tumor necrosis factor family and cytotoxicity were expressed in CD8+ T cells, indicating the killing potential of CD8+ T cells against tumor cells." (PMID 35903095, 2022). "ERY974 increases capecitabine-induced cytotoxicity by promoting capecitabine conversion to its active form by inducing thymidine phosphorylase expression in non-inflamed MKN45 tumour through ERY974-induced IFNγ and TNFα in T cells." (PMID 36071036, 2022). "This, in turn, suggests that CaMKK2 may restrict the abundance of CD40L+ IFNγ+ TNFa+ effector CD4+ TILs, the density of CD4+ cells per mm3 of tumor volume, and the tumor penetrance of CD4+ T cells." (PMID 36309495, 2022). "Besides the direct cytotoxicity against cancer cells, NK cell can release inflammatory cytokines and IFNγ that further trigger activation of innate and adaptive immunity including cytotoxic CD8+ T cell in tumor microenvironment." (PMID 36922936, 2022). "IFNγ downregulates the expression of SLC7A11 and SLC3A2 in tumor cells to inhibit cystine uptake." (PMID 35882850, 2022). "The TIL cultures from LIPO tumour specimens did not yield enough cells for the IFNγ functional assay, thus there were no data points." (PMID 35158816, 2022). "NK cells lyse tumour cells via granzyme and TNFSF10 and FASLG, secrete cytokines, primarily Th‐1 type cytokines such as IFNG, TNF and granulocyte/ monocyte colony‐stimulating factor (CSF2) which facilitate the activation of T cells and other innate immune mediators." (PMID 35445563, 2022). "Although the numbers of total CD8+ T cells remained unchanged, the transcription levels of cytokines IFNγ and TNFα were notably increased in the pyrimethamine group, indicating that CD8+ T cells were activated in the tumor microenvironment after pyrimethamine treatment." (PMID 35262820, 2022). "Firstly, IFNG and EGFR were considered to play a dual role in tumor progression and oncotherapy." (PMID 35692844, 2022). "Interventions with ICI in the time window when treatment would typically occur in patients normalized the tumor vasculature in an IFNγ-dependent manner, with lack of effect using IFNγ receptor knock out mice and upon IFNγ-neutralization studies." (PMID 35712656, 2022).